RB1 (RB transcriptional corepressor 1)
Diseases named in the same sentence as RB1 in open-access papers (continued):
Sharing a sentence is not in itself a finding about the gene and the disease.
prostate carcinoma (continued). "Moreover, the depletion of RB1 from RB1-proficient prostate cancer cells promoted gain of stem cell-like properties through increased expression of interleukin-6 (IL-6) and lysyl oxidase (LOX)." (PMID 34359636, 2021). "Furthermore, in prostate cancers, simultaneous loss of BRCA2 and RB1 sensitizes tumor cells to PARP inhibitor." (PMID 34359636, 2021). "In advanced prostate cancer cases, the co-deletion of RB1 and BRCA2 is frequently found." (PMID 34359636, 2021). "Accordingly, RB1 overexpression is reported to confer sensitivity to CDK4/6 inhibition in prostate cancer, although its loss or deletion is not currently reported as a non-response biomarker." (PMID 32907621, 2020). "The retinoblastoma tumor suppressor gene RB1 is more commonly mutated in metastatic and ADT-recurrent prostate cancer than in primary tumors, while the expression of the ST6GalNAc1 gene is upregulated in primary prostate cancer cells and repressed in patients undergoing androgen deprivation therapy." (PMID 32872551, 2020). "Indeed, we found that RB1 deletion in mouse and human experimental models of prostate cancer also facilitated lineage plasticity with transformation of prostate adenocarcinoma to neuroendocrine (small cell) variants." (PMID 32292420, 2020). "It has been recently reported that RB1 deletion can promote resistance to chemotherapy in prostate cancer; however, as the ELF1 locus is often lost in these same genomic deletions, we asked if ELF1 depletion might contribute to chemotherapy resistance." (PMID 30603056, 2018). "Indeed, accumulation of the active hypophosphorylated form of RB1 seemed to be required for apoptosis induced by matrix contact deprivation in prostate cancer cells." (PMID 26160835, 2015). "During the development of human prostate cancer, chromosome 13q is one of the most frequently deleted chromosomes, and the deletion involves multiple regions and genetic foci in 13q14 and 13q21, including RB1 and FOXO1 at 13q14 and KLF5 at 13q21." (PMID 25896712, 2015).
prostate carcinoma (continued). "General inactivation of the RB1 pathway and deregulation of the cell cycle was a common early event in human cancers, however homozygous deletion of RB1 is a relatively late-stage genomic alteration in acinar prostate cancer progression." (PMID 25937998, 2015). "Overall, these data suggest that, although loss of Notch signaling may be important for regulating NE differentiation in prostate cancer, loss of Notch was not sufficient to drive NE differentiation of PCa even in the context of concurrent RB1 loss." (PMID 39024561, 2024). "RB1 deficiency and/or replication stress, characteristics of poor prognosis, and conferred sensitivity were associated with complete tumor regression in both neuroendocrine (NEPC) and androgen receptor positive (ARPC) prostate cancer models, even with low B7H3 levels." (PMID 37725435, 2023). "Moreover, RB1 regulates NF-kB and inhibits NF-kB transcriptional activity in prostate cancer." (PMID 36232606, 2022). "In particular, RB1 knockdown has been shown to enhance the sensitivity to cell death induced by different anticancer agents, such as DNA-damaging and microtubule interfering agents, in cells from several cancer types, including lymphoma, breast, lung, and prostate cancer, and glioblastoma." (PMID 26160835, 2015). "Therefore, RB1 status seems to have a key role in cellular response to therapeutic interventions in prostate cancer cells and could represent a marker for directing therapy also in this tumor type." (PMID 26160835, 2015). "Further mechanistic studies revealed that CDC20, DTL, and RRM2 were transcriptionally regulated by the RB1/E2F1 axis, mediating cell cycle progression in prostate cancer." (PMID 41492471, 2026). "Recent studies indicate that HDAC5 inhibitors boost RB1 expression and sensitise CDK4/6 inhibitors in prostate cancer cells." (PMID 40070134, 2025). "Analysis of CNA clonality has shown NKX3-1 deletion, RB1 deletion, FOXP1 deletion, and ERG rearrangement are the earliest forms of structural variation occurring in prostate cancer evolution." (PMID 40840524, 2025).
prostate carcinoma (continued). "Whole tumor biopsies from multiple cohorts of patients with advanced prostate cancer were interrogated using whole-exome sequencing (WES), RNA-Seq (bulk and single nucleus), and IHC for RNASEH2B and RB1." (PMID 38833311, 2024). "RB1 (a regulator of cell cycle G0/G1 phase) and PTEN are other most frequently altered genes in advanced prostate cancer." (PMID 38254807, 2024). "This study aimed to evaluate the combined effect of downregulated RB1 and overexpressed SSTR5-AS1 as biomarkers for predicting time to castration-resistant prostate cancer." (PMID 35420053, 2022). "This study has shown that the combined effect of low expression of RB1 and high expression SSTRS-AS1 provides promising parameters for predicting worse outcomes of castration as a single therapy in prostate cancer." (PMID 35420053, 2022). "The synthetic lethal interaction between RB1 and TSC2 was also a case in multiple human prostate cancer cell lines." (PMID 34359636, 2021). "We used the following previously characterized pairs: RB1-wt PC3 and RB1-mutant DU145 prostate cancer cells, RB1-wt U2OS and RB1-mutant Saos-2 osteosarcoma cells, and RB1-wt MDA-MB-231 and RB1-mutant MDA-MB-468 triple negative breast cancer cells." (PMID 33591981, 2021). "According to our results, UBE2C highly expressed in prostate cancer, especially in castration-resistant prostate cancer and UBE2C was correlated with the neuroendocrine prostate cancer biomarkers, such as RB1 and LDHA." (PMID 33630978, 2021). "The kind of mutated genes in PSs and MSs was similar, such as tumor suppressor gene BRCA2 and RB1, but the alteration frequency had typically declined in PSs, which might suggest that genes in chromosome 13 play an important role in tumor metastasis as reported in prostate cancer." (PMID 33014052, 2020).
prostate carcinoma (continued). "Additionally, the research demonstrated that PARPis Olaparib and Talazoparib significantly hamper the growth of prostate cancer cell lines and organoids derived from human mCRPC exhibiting both homozygous and heterozygous co-deletion of BRCA2 and RB1." (PMID 38672640, 2024). "We therefore investigated the expression of RB1 and AURKB in prostate cancer tissues." (PMID 35853811, 2022). "In primary/non-metastatic prostate cancers, RB1 deletion is identified with less than 10% prevalence, but this rises to higher than 30% in those attaining metastatic and/or castration-resistant phenotypes." (PMID 34359636, 2021). "Probably, this explains why RB1-SUCLA2 co-deletion is not quite prevalent in cancers other than prostate cancer." (PMID 34359636, 2021). "The combined effect of cell cycle deregulation via RB1 and E2F1 and of AR re-activation was hypothesized to promote prostate cancer progression to castration resistance." (PMID 25575823, 2015).
prostate carcinoma (continued). "The roles of RB1 in suppressing malignant progression of prostate cancer may not be solely explained by its primary function to constrain cell cycle progression." (PMID 34359636, 2021). "In addition, stratified analysis showed that lower mRNA RB1 expression was significantly associated with shorter CRPC both in metastatic (p = 0.017) and non-metastatic (p = 0.001) prostate cancer patients." (PMID 33299560, 2020). "Furthermore, high AR levels transcriptionally suppress DNA replication in prostate cancer cells; this activity is increased in CRPC cells expressing high AR levels and is mediated by recruitment of hypophosphorylated RB1; however, AR stimulates also DNA replication through AR hyperphosphorylation." (PMID 31366128, 2019). "Prostate cancer does not show an evident co-occurrence pattern, and almost all edges have a weight of 1, however, there were some central nodes including CTNNB1, RB1, and AR." (PMID 39040139, 2024). "Conversely, common RB1 and PTEN alterations in prostate cancer are copy number losses which manifest as negative expression in IHC." (PMID 38136389, 2023).